EGFR (epidermal growth factor receptor)
Diseases named in the same sentence as EGFR in open-access papers (continued):
Sharing a sentence is not in itself a finding about the gene and the disease.
tumor (continued). "Although few patients shared similar tumor mutational profiles, common pathways in unresponsive cases included those of regulation of cell cycle progress, PI3K/Akt and mTOR signaling, EGFR tyrosine kinase inhibitor resistance." (PMID 31717320, 2019). "Taken together, these data suggested that VPS33B acted as a potential tumor suppressor that participated in the suppression of the EGFR/PI3K/AKT-induced cell cycle signaling cascade." (PMID 30944308, 2019). "Reduction of [18F]FDG-uptake as shown in our study following incubation of tumor cells with 213Bi-anti-EGFR-MAb, was also shown previously as a result of cytotoxic therapy." (PMID 31165773, 2019). "The uptake level of [111In]In-DOTA-cetuximab in the EGFR highly-overexpressed HCC827 tumor (n = 7) was significantly higher than those in other cell lines except for EBC-1 (26.9 ± 3.10%ID/g, P < 0.05)." (PMID 31651282, 2019). "There was also inverse correlations between EGFR expression, lymph node involvement, and tumor depth of invasion." (PMID 31470870, 2019). "TNuF was experimentally shown to suppress metastasis of tumor cells and expression of tumor-induced VEGF as well as expression of EGFR, HIF-1α and CD31 in lung tissues." (PMID 31426614, 2019). "We used IHC to determine pH3 levels in 68 pretreatment tumor samples and 24 re-biopsies after relapse to EGFR TKIs from EGFR-mut patients." (PMID 31000705, 2019). "This suggests that the tumor tissue accumulation of Ame55 is helpful for EGFR pathway inhibition, but the role was still limited." (PMID 30733972, 2019). "Another independent research on MCF-7 cells showed that soluble factors secreted by fibroblast rescued the tumor cells from tamoxifen by the mechanisms that involved EGFR and matrix metalloproteinases]." (PMID 30680600, 2019). "Together with the EGFR signaling pathway in tumor cells considered in our previous studies, we have developed a multiscale agent-based model for the angiogenesis-tumor system." (PMID 31074391, 2019). "In parallel, a recent study demonstrated that inhibition of the EGF/EGFR signaling axis reduced spheroid formation between ATCs and macrophages, and eventually attenuated OC tumor growth in a mouse model." (PMID 30710055, 2019). "We also found EGFR mutations distribution was heterogeneous in different regions of same tumor by multi-regions ARMS detection, and only the regions with higher ions intensity of phospholipids were EGFR-mutated-positive." (PMID 31555581, 2019). "Ablation of Integrin α3 expression inhibited tumor growth through blockade of epidermal growth factor receptor (EGFR) signaling pathway accompanied by altered leucine-rich repeats and immunoglobulin-like domain protein 1 (LRIG1) expression." (PMID 31137693, 2019). "Distinguishably high accumulation of radiolabeled cetuximab was noted in EGFR-highly-overexpressing tumors in comparison to the tumors with low and moderate EGFR expression levels, allowing for clear visualization of the tumor in PET imaging." (PMID 31651282, 2019). "There was strong selective tumor accumulation and localization in the EGFR‐positive KYSE520 tumors with LR004 and LR004‐VC‐MMAE." (PMID 30372581, 2019). "Upregulation of AXL expression in tumor tissue was apparent after the development of EGFR‐TKI resistance in patients of the present study." (PMID 31419057, 2019). "Analysing CTCs and ctDNA in patients with CRC allows us to choose the best therapy with respect to the tumour mutations identified: presence of RAS mutations, Anti-Epidermal Growth Factor Receptor (anti-EGFR) mutations, and BRAF mutations." (PMID 31930130, 2019). "The evolution of a same tumour from adenocarcinoma to squamous cell carcinoma along the administration of anti-EGFR drugs is a mechanism of acquired drug resistance." (PMID 31795465, 2019).
tumor (continued). "Secondly, in antibody-treated A431 cell xenograft tumor tissues, Ame55 has increased inhibition of the EGFR pathway, including total EGFR, pEGFR Y1068, and its downstream pAKT and pERK1/2, but the inhibition effect is still less than that of cetuximab." (PMID 30733972, 2019). "We also noted that EGFR-expressing tumor discs have abnormally extensive tracheation (respiratory tubes) and ectopically express Branchless (Bnl, a FGF) and FGFR." (PMID 31568500, 2019). "Nevertheless, tumor flares have been reported in patients who discontinued an EGFR-TKI because of disease progression or inability to tolerate treatment, as well as in patients with progression while on EGFR-TKI who have responded after treatment." (PMID 31720896, 2019). "We propose to target the survival signaling machinery as the secondary “Achilles’ heel” in the early adaptive drug persister tumor cells in combination with EGFR-TKIs to more effectively eradicate the minimal residual drug persister tumor cells." (PMID 31815659, 2019). "A recent study has demonstrated that microRNA-338-3p/EYA2 axis led to epidermal growth factor receptor (EGFR)-induced tumor growth and lung metastasis." (PMID 30761270, 2019). "To identify the cell types in the tumor mass that expressed both activin A and EGFR, we performed immunohistochemical staining of tissue sections from 155 patients with OSCC." (PMID 30914776, 2019). "The CSF cells from the individual (patient #12) without matching CSF cfDNA sample had a mutation of EGFR E746_A750del, which was in agreement to the EGFR 19del identified in the primary tumor by the ARMS technology." (PMID 30755180, 2019). "The EGFR exon 21 was successfully amplified by nested-PCR in 120 tumor cells, including 61 cells from the short PFS group and 59 cells from the long PFS group." (PMID 31014278, 2019). "Then, we screened various types of tumor cells with different EGFR expression levels and assessed the antitumor activities of LR004‐VC‐MMAE in vitro." (PMID 30372581, 2019). "In the mouse model of EGFR-mutated NSCLC, osimertinib had antitumor activity in tumours driven by EGFRL858R mutation comparable to that of afatinib, but it was more effective than afatinib in EGFR double mutants, L858R/T790M or exon 19 del/T790M EGFR." (PMID 31739412, 2019). "Meanwhile, we used EGFR inhibitors to treat A549 bearing nude mice and sort the residual tumor cells." (PMID 31316001, 2019). "Without any known actionable mutations were detected in the five samples, such as EGFR, KRAS, BRAF, HER2, and EML4‐ALK in the tumor tissues." (PMID 30941903, 2019). "Twenty-four were positive for EGFR mutations (EGFR-mutated) and 24 for KRAS mutations (KRAS-mutated) in tumor specimens." (PMID 31861832, 2019). "In vivo tumor imaging in mice indicated an increase in methylene blue signal over time and a higher intensity for EGFR-targeted nanoparticles compared to untargeted nanoparticles." (PMID 31561451, 2019). "Our results indicate clear associations between 1) p16 positivity with disease-specific survival; 2) total EGFR tumour levels with disease-specific survival; and 3) EGFR over-expression and smoking status." (PMID 30630536, 2019). "Some studies have also suggested that the site of the primary tumor predicts for the efficacy of anti-EGFR monoclonal antibodies, with this being restricted to RAS wt LCC 28-34." (PMID 31762802, 2019). "One tumour (ID-87) with P63 expression also showed very high levels of EGFR and KRT5, highly suggestive of squamous cell differentiation." (PMID 31537838, 2019).
tumor (continued). "Further scrutiny of dm1 structure reveals that there is still a portion of dm1 carrying wild-type EGFR (wtEGFR), suggesting that dmIII in the relapse tumor is likely inherited from dm1 in the diagnosis tumor (see the next section for detailed analysis)." (PMID 30267146, 2019). "There were significant decreases in p‐AKT/AKT, p‐mTOR/mTOR, and PD‐L1 in DTLL‐treated tumor samples with the same inhibitory trends in the ratios of p‐EGFR/EGFR and p‐HER2/HER2." (PMID 30681288, 2019). "Among the downregulated genes in PMDs are EGFR (epidermal growth factor receptor) and PDGFRA (platelet-derived growth factor receptor α) that have tumor promoting mutations." (PMID 30988298, 2019). "We present a comprehensive analysis of co-occurring genetic aberrations in pretreatment and post-treatment tumor tissue and their contribution to innate resistance (IR) and AR to three third-generation EGFR TKIs." (PMID 32914023, 2019). "Microscopic analysis of metastatic LNs demonstrated a clear correlation between EGFR expression and panitumumab-IRDye800CW uptake on the tumor cell membranes in macro-metastases and micro-metastases." (PMID 31695030, 2019). "In fact, the E2F1 levels were found upregulated in the corticotroph tumor cells, whereas they were abrogated by EGFR inhibition." (PMID 31487906, 2019). "It plays major functions in tumor cell survival and activated phosphorylation of EGFR leads to the phosphorylation of downstream proteins that contribute to metastasis, invasion, cell proliferation and inhibition of apoptosis." (PMID 31123430, 2019). "(D) Western blot analysis of tumor lysates for phosphorylated EGFR (P-EGFR), phosphorylated STAT3 (P-STAT3), BAX." (PMID 30674340, 2019). "We ensured that EGFR806-CAR T cells are able to lyse tumor cells with a wide range of EGFR expression levels." (PMID 31903167, 2019). "Tumor and wildtype organoids established from the same patient were subjected in parallel to EGFR-targeted PDT." (PMID 31694307, 2019). "In these circumstances, a combination of MEK and EGFR inhibitors was tested, leading to significant anti-tumor activity." (PMID 31652660, 2019). "Evidences have been provided suggesting that primary tumor location is not only prognostic, but also predictive of the efficacy of anti-EGFR agents." (PMID 31762802, 2019). "Pre-clinical studies have shown that treatment with cetuximab alone and in combination with radiotherapy increases survival in vivo and can also completely eliminate tumours in EGFR-amplified PDX models." (PMID 31616641, 2019). "EGFR amplification and PTEN mutation are the most common mutations and are highly correlated with tumor angiogenesis in GBM." (PMID 30769863, 2019). "We have recently reported the generation of an oncolytic adenovirus armed with a BiTE targeting the EGFR on tumor cells (ICO15K-cBiTE)." (PMID 30683154, 2019). "p-FGFR level was also significantly increased, which suggests that CD166+ OSCs exhibited a switch from EGFR to activation of an alternative tumor cell- specific RTKs (FGFR)." (PMID 31138318, 2019). "The significant tumor growth inhibition in combination-treated mice was mediated by reduced total and active levels of HER2, EGFR, and c-Met, compared to individual OC or LP treatments, suggesting effective tumor cell sensitization." (PMID 30781364, 2019). "More importantly, the Cilen and EGFR drugs loaded MPEG-PLA nanoparticles also reveal superior tumor growth inhibition along with reduced systemic toxicity, which provides a potential strategy in clinical EGFR-resistant NSCLC treatment." (PMID 31316001, 2019). "Q61L was one of the hotspots in the KRAS gene and has been confirmed to influence response to EGFR antagonists for tumor patients." (PMID 30755180, 2019). "A possible explanation for this phenomenon is that EGFR-mutated NSCLCs are associated with an uninflamed phenotype and weak immunogenicity, exhibiting lower PD-L1 expression/CD8+ TILs in the tumor microenvironment." (PMID 30901844, 2019).
tumor (continued). "The increased level of EGFR and vascular related proteins would stimulate tumor cell proliferation and angiogenesis, thereby facilitating tumor cell growth and metastasis." (PMID 31426614, 2019). "For example, the clinical decision making of EGFR-TKI is normally based upon tumor genotyping to identify the existence of EGFR sensitive mutations." (PMID 31451693, 2019). "Most importantly, HDAC inhibitors, such as TSA, can induce the proteasome degradation of EGFR, which in turn inactivating Arf1, leading to suppression of tumor-promoting activity." (PMID 30777099, 2019). "Our findings suggest miR-141 acts as a tumor suppressor by targeting EGFR expression in HNSCC cells." (PMID 30737360, 2019). "Studies found a significant association between the tumor uptake of copper-64 (64Cu) labeled cetuximab ([64Cu]Cu-DOTA-cetuximab) and the expression levels of EGFR protein in cervical cancer cell lines and in xenograft mouse models with various cancer types." (PMID 31651282, 2019). "Following delivery into the tumour, liposomes are internalised into EGFR-overexpressing cells via the EGF present on their surface ensuring co-delivery of Dox and 111In." (PMID 31534505, 2019). "In this section, we aimed to investigate the evolution of the EGFR-carrying double minutes from the diagnosis tumor to the relapse tumor." (PMID 30267146, 2019). "IHC results showed that the expressions of ERα, ERβ, EGFR and Notch1 in tumor tissues were higher than those in adjacent normal tissues." (PMID 31511014, 2019). "Among the compounds herein described, 7h is a potent inhibitor of EGFRwt and E.GFRL858R in the nanomolar range and showed cellular cytotoxic activity (>80% at 10 μM) on Oncotest® patient-derived tumor cell lines, while being selective for EGFR related cells." (PMID 30626888, 2019). "The expression of these biomarkers were determined in tumours from 70 patients with metastatic CRC by immunohistochemistry, and in a panel of human CRC cell lines, and their variants with acquired-resistance to EGFR inhibitors, by flow cytometry." (PMID 30899442, 2019). "EGFR overexpression has also been demonstrated to play a major part in cancer progression, especially in tumor invasiveness and aggressiveness." (PMID 30996686, 2019). "We next examined the effects of uPAR knockdown in combination with EGFR inhibition on tumor growth in vivo." (PMID 31434965, 2019). "The associations found were weak or moderate; there were notable differences in tumor-size kinetics between antiangiogenic agents and anti–epidermal growth factor receptor agents." (PMID 31539075, 2019). "Only the tumor sample showed a signal of EGFR-FITC-SiO2-NPs while the FITC-SiO2-NPs (controls) exhibited no signal." (PMID 31561451, 2019). "Upregulation of the receptor tyrosine kinase AXL in tumor tissue has been detected in about one‐fifth of NSCLC patients with acquired resistance to EGFR‐TKIs." (PMID 31419057, 2019). "Rociletinib (CO-1686), sharing common structural features with osimertinib, promotes tumour regression in tumour xenograft and transgenic models, and is currently being evaluated in phase I/II clinical trials in EGFR-mutant NSCLC." (PMID 31739412, 2019). "It is a puzzle why EGFR targeted therapy has poor performance in TNBC—a tumor characterized by high EGFR overexpression." (PMID 31443516, 2019). "In RET or EGFR expressing models, vandetanib showed a remarkable tumor regression, an effect ascribed to inhibition of RET or EGFR phosphorylation and downstream signaling pathways." (PMID 35582269, 2019). "There was no statistical difference in brain MR imaging tumor characteristics, tumor locations or other extracranial metastatic sites among three different EGFR-TKI groups." (PMID 31415376, 2019).
tumor (continued). "The TME of EGFR mutated NSCLC, as in other tumours, includes several cells of the immune system: tumour-associated macrophage (TAM), T cell CD4+, CD8+, regulatory T cell (Treg FOXP3+), and mast cells." (PMID 31554160, 2019). "Genes within the EGFR signaling pathway have been shown to be frequently altered at both genomic and protein levels, contributing to tumor growth and progression of ampullary pancreatic carcinoma." (PMID 31150430, 2019). "Other drugs used in cancer treatment infiltrate the tumour cells and inhibit the activation of some proteins in the EGFR/ERK cascade." (PMID 31016574, 2019). "In the past, conventional molecular pathology detection of EGFR mutations mostly relied on ARMS and sediment tumors tumor cells were mainly used in the case of body fluid‐derived specimens." (PMID 31602787, 2019). "Although EGFR is an essential target of long-established and successful tumor therapeutics, the exact function and biomarker potential of alternative EGFR isoforms II-IV are unclear, motivating more in-depth analyses." (PMID 31438847, 2019). "EGFR is highly expressed in both TNBC tumours and cell lines, supporting a role for EGFR as an oncogenic driver in TNBC." (PMID 31262335, 2019). "In addtion, combination of JQ1 with EGFR inhibitors significantly enhanced the anti-tumor effect in vitro and in vivo." (PMID 30770740, 2019). "Forty formalin-fixed, paraffin-embedded NSCLC tumour cases (20 EGFR mutant and EGFR 20 wild type) were analysed by the IdyllaTM EGFR Mutation Test (CE-IVD) and compared with PCR and NGS methodologies." (PMID 30470932, 2019). "The PI3K/AKT pathway is closely related to the proliferation, differentiation, apoptosis, migration, and adhesion of tumor cells involving multiple targets, including EGFR, BCL2, GSK3B, CDK2, and CDK4." (PMID 31406500, 2019). "It has been recently reported that EGFR signaling regulates tumor cell metabolism to promote tumor growth." (PMID 30824700, 2019). "Gefitinib, an epidermal growth factor receptor (EGFR) inhibitor has been shown to reduce tumor size in NSCLC that express high levels of EGFR receptor." (PMID 31263479, 2019). "The sensitivity, specificity and consistency of EGFR detection using exosomes were evaluated, compared with gene detection using tumor tissues and cell blocks." (PMID 31608233, 2019). "It has been shown that GBM tumor cells with EGFR amplification have higher infiltration ability and inhibition of EGFR activity suppresses tumor cell growth." (PMID 31531345, 2019). "In conclusion, our studies revealed that HER2 and EGFR are highly expressed in ovarian metastases and primary tumours of CRC patients with ovarian metastases." (PMID 30858756, 2019). "Common mechanisms include secondary EGFR mutations, such as T790M, bypass receptor tyrosine kinase activation, such as through MET amplification, or tumour reprogramming through epithelial–mesenchymal transition or transformation to small cell lung cancer." (PMID 30880334, 2019). "Increasing awareness of an essential contribution by innate immunity in tumor immune surveillance and in metastasis control is advocated whereby new immunotherapeutic options are becoming available for management of relapsed EGFR mutant patients." (PMID 32082304, 2019). "Dramatic tumor response and favorable clinical outcomes led to their widespread use in the first-line setting for patients with advanced NSCLC harboring activating EGFR mutation (a deletion in exon 19 or the L858R mutation in exon 21)." (PMID 31196210, 2019). "These molecular markers used for the selection of anti-EGFR therapy were preserved in the patient tumor tissue as well as in the tumor derived primary cell line MBC02." (PMID 30828563, 2019). "This tumor specificity is likely due to changes in steric accessibility of the mAb806 epitope between tumor-expressed and wild type EGFR." (PMID 31903167, 2019).